Y_RNA (Y RNA )
Gene: Miscellaneous RNA gene on chromosome 7 (75,297,990 to 75,298,091, reverse strand). Ensembl gene ENSG00000267828.
Homologues: Orthologues: chimpanzee Y_RNA (99% identical), pig Y_RNA (75% identical). Paralogues in human: Y_RNA (100% identical), Y_RNA (97% identical), Y_RNA (93% identical), Y_RNA (92% identical), Y_RNA (90% identical), Y_RNA (89% identical), Y_RNA (87% identical), Y_RNA (85% identical), RNY3 (84% identical), RNY3P12 (84% identical), Y_RNA (84% identical), RNY3P1 (83% identical), and 98 more.